DES (desmin)
Diseases named in the same sentence as DES in open-access papers (continued):
Sharing a sentence is not in itself a finding about the gene and the disease.
leiomyosarcoma (continued). "In our case, leiomyosarcoma was ruled out because the tumor tested negative for desmin and calponin." (PMID 39171331, 2024). "Specifically, the two tumors clustering near leiomyoma/leiomyosarcoma were both negative for Desmin and H-Caldesmon." (PMID 39392508, 2024). "The absence of desmin also ruled out leiomyosarcoma and negative DOG1 staining excluded gastrointestinal stromal tumor." (PMID 39376807, 2024). "A histological diagnosis of high-grade leiomyosarcoma was made on the basis of histology, positivity for caldesmon and desmin, and negative cytokeratin immunostaining." (PMID 37859906, 2023). "Leiomyosarcomas showed diffuse and strong immunoreactivity for SMA and desmin." (PMID 35001360, 2022). "The spindle cells were negative for actin, desmin, Myod1, and myogenin, excluding leiomyosarcoma or rhabdomyosarcoma, and they were also negative for CD21 and CD35, excluding follicular dendritic sarcoma." (PMID 34940081, 2021). "Leiomyosarcomas show smooth muscle cytomorphology and are positive for SMA, caldesmon, and desmin." (PMID 32867125, 2020). "The positivity for smooth muscle actin and desmin immunohistochemistry confirmed the muscular origin of the tumour cells and there were no features of malignancy to suggest leiomyosarcoma." (PMID 27999705, 2016). "In fact, leiomyosarcomas are composed of cells that consistently express smooth cell actin and desmin, but they are negative for CD34 and CD117, these last are positive in the case of GIST." (PMID 27633779, 2016). "Usually, leiomyosarcoma cells are positive for smooth muscle actin, weakly positive for desmin and negative for S100 protein." (PMID 24959258, 2014). "In their report, these dedifferentiated leiomyosarcomas lacked the characteristic immunohistochemical staining of differentiated leiomyosarcoma for muscle-specific actin, smooth muscle actin, desmin, and CD34." (PMID 25580348, 2014). "These were 7 tests for h-caldesmon (for leiomyosarcoma), 3 CDK4 (for WDL/DDL), 2 DOG1 (for GIST), 2 beta-catenin (for fibromatosis), 1 each of CD34 (DFSP), desmin, myogenin (rhabdomyosarcoma (RMS)), p63 (sarcomatoid carcinoma), PSAP (prostatic carcinoma), and TLE1 (synovial sarcoma)." (PMID 25165418, 2014). "Desmin and muscle-specific actin, which are good markers of leiomyosarcomas, are never expressed in UTCs." (PMID 23445571, 2013). "And desmin or h-caldesmon are very useful markers for differential diagnosis, which are positive in leiomyosarcomas and negative in NSCD10s." (PMID 23356903, 2013). "Immunohistochemically, leiomyosarcomas are nearly uniformly positive for smooth muscle actin, desmin, and vimentin and negative for calretinin, carcinoembryonic antigen, cytokeratin, leukocyte common antigen, neuroendocrine filament, CD-117, and S-100 protein." (PMID 22480303, 2012). "Leiomyomas and leiomyosarcomas characteristically demonstrate expression of muscle markers such as desmin and smooth muscle actin, and our case was negative for both of these markers." (PMID 21437510, 2011). "Leiomyomas and leiomyosarcomas are differentiated from GISTs by positive immunoreactivity for desmin and smooth muscle actin and negative immunoreactivity for C-KIT (CD117) and CD34." (PMID 20307271, 2010). "Immunostains for smooth muscle actin and desmin were positive and those for melanoma and cytokeratin were negative, consistent with the diagnosis of leiomyosarcoma." (PMID 20178598, 2010). "On IHC bases, both leiomyoma and leiomyosarcoma were positive for both SMA and desmin." (PMID 16859566, 2006). "However, extended immunohistochemical studies later demonstrated diffuse positivity for DOG1 and smooth muscle actin (SMA), with negative staining for CD117, CD34, S100, and desmin, raising suspicion for a leiomyosarcoma-type gastric stromal tumor." (PMID 41209937, 2025). "The absence of Desmin and S100 helps exclude leiomyosarcoma and nerve sheath tumors, respectively." (PMID 40686513, 2025).
leiomyosarcoma (continued). "Therefore, we again performed IF staining of tumor sections to examine the expression of leiomyosarcoma markers, including vimentin, α–smooth muscle actin (α-SMA), caldesmon, and desmin, at the xenograft site, with the detected signals supporting these as leiomyosarcoma." (PMID 38451719, 2024). "HHF 35, αSMA, Vimentin, Desmin, H-Caldesmon positivity in the low to high grade Leiomyosarcoma component, while the dedifferentiated component may not show any of the myogenic marker reactivity." (PMID 36777814, 2023). "UPSs lack areas of conventional leiomyosarcoma and are negative for desmin and caldesmon." (PMID 32867125, 2020). "For example, leiomyosarcomas stain positive for desmin, whereas NF does not." (PMID 33296059, 2020). "Additionally, leiomyosarcoma shows reactivity to Desmin, Actin and Myogenin, but vascular markers are not expressed." (PMID 31311568, 2019). "The neoplastic cells of leiomyomas and leiomyosarcomas are strongly and diffusely positive for smooth muscle actin and desmin but negative for CD34 and CD117 while GISTs are strongly and diffusely positive for CD117, with a cytoplasmic, membranous, or paranuclear “dot-like” pattern." (PMID 31439993, 2019). "Because of its rarity, the immunohistochemical analysis with desmin, inhibin α-smooth muscle actin or histochemical staining with Masson′s trichrome is recommended to rule out the differential diagnosis especially leiomyosarcoma and sex-cord stromal tumors (thecoma and sclerosing stromal tumor)." (PMID 26175813, 2015). "Additionally, the majority of leiomyosarcomas express desmin, in contrast to CCMMTs, which are desmin negative." (PMID 26698563, 2015). "Epithelioid sarcomas are easily distinguished from leiomyosarcomas by their lacking a representative area of a leiomyosarcoma, showing fascicles of elongated tumor cells with blunt-ended "cigar-shaped" atypical nuclei, and greater frequency of negativity for desmin and SMA." (PMID 23886403, 2013). "Leiomyosarcoma tumor cells typically show positive staining for SMA, desmin, calponin, and h-caldesmon and negative staining for CK, S-100 protein, HMB-45, and CD117 (c-KIT)." (PMID 40755625, 2025). "Immunohistochemical analysis of the right ventricular outflow tract mass confirmed the presence of tumor cells that were positive for Desmin and smooth muscle actin (SMA), while negative for S-100 and myoglobin, leading to a diagnosis of leiomyosarcoma." (PMID 40556659, 2025). "Pleomorphic leiomyosarcomas lack components of WDLPS and are positive for SMA and desmin but negative for MDM2 and CDK4." (PMID 32867125, 2020). "On the contrary, leiomyosarcomas of the colon were all negative for CD34 and c-kit but most of them showed positivity for SMA, desmin, or both." (PMID 30654838, 2019). "In leiomyosarcoma, tumor cells are positive for α-SMA, desmin, and vimentin and negative for cytokeratin, epithelial membrane antigen, and S-100." (PMID 26380169, 2015). "Immunohistochemistry of retroperitoneal leiomyosarcoma shows positive for SMA and desmin and negative for CD117, S-100, HMB45 and CD34, which are of benefit to differentiate leiomyosarcoma from other soft tissue tumors." (PMID 24396471, 2014). "The nonreactivity of the tumor for SMA, desmin, CD34 and CD117 in our five cases argues against the diagnoses of leiomyosarcoma, rhabdomyosarcoma, solitary fibrous tumor and gastrointestinal stromal tumor." (PMID 22862905, 2012). "Leiomyosarcomas are typically positive for smooth muscle actin (SMA), desmin, and h-caldesmon, and negative for epithelial markers like cytokeratin (CK) or epithelial membrane antigen (EMA), helping to distinguish them from sarcomatoid urothelial carcinoma or inflammatory myofibroblastic tumors." (PMID 40943759, 2025).
leiomyosarcoma (continued). "In the case of the right ventricular outflow tract mass, immunohistochemistry confirmed the presence of tumor cells that exhibited positive staining for Desmin and SMA, while showing negative staining for S-100 and myoglobin, leading to a diagnosis of leiomyosarcoma." (PMID 40556659, 2025). "The last case showing exclusively spindle cell morphology reveals intense and diffuse reaction for vimentin and smooth muscle actin, with only focal-positive expression for desmin; CKs and CD10 are negative and, therefore, based on this immune profile, this tumour is diagnosed as leiomyosarcoma." (PMID 29182526, 2017).
rhabdomyosarcoma (93 papers, 1987 to 2026). A rare aggressive malignant mesenchymal neoplasm arising from skeletal muscle. "The primitive-looking tiny round cells expressing desmin in rhabdomyosarcoma match diagnostic criteria, but the localized expression of NKX 2.2 adds an intriguing feature." (PMID 38234938, 2023). "The diagnostic and prognostic relevance of desmin expression in 80 rhabdomyosarcomas (RMS) and 5 embryonal sarcomas (ES) was examined using a peroxidase anti-peroxidase staining procedure." (PMID 3311112, 1987). "If the patient is accompanied by heterologous sarcoma components, such as rhabdomyosarcoma components with positive expressions of Desmin, Myogenin, and MyoD1, the risk of recurrence may increase." (PMID 38783282, 2024). "Interestingly, CD97 was present in all subtypes of rhabdomyosarcomas and thus seems to be closely associated with this malignant tumor type, perhaps even more than muscle-specific actin and desmin." (PMID 24949957, 2014). "Immunohistochemical(IHC) staining confirmed diffuse positivity for skeletal muscle lineage markers(desmin, myogenin, MyoD1) in the tumor cells, thereby establishing a definitive diagnosis of rhabdomyosarcoma." (PMID 41783407, 2026). "Rhabdomyosarcoma typically shows positive staining for myogenin, desmin, sarcomeric actin, and myoglobin, while it is usually negative for NKX2.2, CD99, CD45, cytokeratin (CK), S100, and neuron-specific enolase (NSE)." (PMID 40094002, 2025). "This can also mimic lymphoma (CD45+), poorly differentiated carcinoma (cytokeratin+), GIST (DOG1/CD117+), and rhabdomyosarcoma (desmin/myogenin+)." (PMID 41458270, 2025). "For example, lymphoma is typically positive for leukocyte common antigen (CD45), whereas rhabdomyosarcoma expresses desmin and myogenin." (PMID 40084340, 2025). "A percutaneous biopsy of the abdominal mass identified a poorly differentiated round cell malignancy, Desmin-positive, consistent with alveolar rhabdomyosarcoma." (PMID 40630346, 2025). "Rhabdomyosarcoma expresses desmin, MyoD1, or myogenin due to skeletal muscle differentiation, whereas small cell carcinoma expresses CK and CgA with or without Syn." (PMID 40978053, 2025). "Rhabdomyosarcoma presented primitive cells expressing desmin, and NKX 2.2 focal expression echoed previous subtype-associated studies." (PMID 38234938, 2023). "The neoplastic cells of rhabdomyosarcoma were positive for vimentin, desmin, myoglobin and muscle-specific actin." (PMID 36641746, 2023). "On IHC staining, the neoplastic cells in pleomorphic rhabdomyosarcoma show positive reactivity with myogenin, desmin, smooth muscle actin (SMA) and vimentin." (PMID 34034720, 2021). "Immunohistochemical staining showed strong positivity for desmin in the rhabdomyosarcoma differentiation components in two cases." (PMID 34631758, 2021). "The TE671 human cell line is derived from rhabdomyosarcoma and naturally expresses muscle-type nicotinic acetylcholine receptors (nAChR) and desmin, an intermediate filament protein." (PMID 30634526, 2019). "A hallmark of rhabdomyosarcoma is that tumors express early markers along the skeletal muscle lineage such as MYOD1, MYOG and Desmin; however, these tumors fail to terminally differentiate indicating a developmental arrest." (PMID 29869612, 2018). "Alterations in desmin abundance or PTMs in rhabdomyosarcoma TE671 cells that have decreased its interaction with DUX4/4c have most probably allowed us to detect other protein partners on these more accessible targets." (PMID 26816005, 2016). "In rhabdomyosarcoma, certain cells exhibit red pigmentation in the cytoplasm, and the immunohistochemical expression pattern is desmin(+)/muscle regulatory protein MyoDl(+)/NSE(−)." (PMID 25435930, 2015). "Small numbers of these cases were assigned provisional diagnoses, for example, rhabdomyosarcoma, if there was focal expression of appropriate markers (e.g., clear cut desmin with myogenin or MyoD1)." (PMID 25810689, 2015).
rhabdomyosarcoma (continued). "Muscle-specific markers such as desmin, myogenin, or myo-D1, characteristic of rhabdomyosarcoma, should be included in the immunohistochemical study." (PMID 25475214, 2014). "Of the 36 tumors, 2 (5.5%) had positive results for desmin and coexpressed nuclear myoD1, confirmed the diagnosis of rhabdomyosarcoma." (PMID 24349741, 2013). "Contrarily, pediatric cases of sclerosing rhabdomyosarcoma expressed strong immunopositivity for all muscle markers, including MyoD1, Myogenin, Desmin and SMA, most likely reflecting a different stage of muscle maturity." (PMID 20701800, 2010). "Notably, the components of rhabdomyosarcoma exhibited a strong positive reaction for desmin and a moderate positive response for myoglobin, the undifferentiated spindle cell component demonstrated a positive immunoreactivity solely for vimentin." (PMID 40832615, 2025). "In addition, DSFTs can exhibit aberrant immunophenotypes due to their heterogeneous differentiation, such as the presence of desmin and myogenin in the embryonal rhabdomyosarcoma component." (PMID 40432917, 2025). "Immunohistochemistry showed positivity for rhabdomyosarcoma markers such as Desmin, MyoD1, and Myogenin in the rhabdomyosarcomatous component and positivity for neuroectodermal markers, including synaptophysin and chromogranin A in the neuroectodermal component." (PMID 41465905, 2025). "Desmin, myogenin, and MyoD1 help identify rhabdomyosarcoma components." (PMID 39450250, 2024). "Historically, rhabdomyosarcoma at our center has been more of a morphological diagnosis with further validation of diagnosis and or subtype by using immunohistochemical stains such as Desmin, Myogenin, and myoD1." (PMID 35942988, 2023). "Rhabdomyosarcomas expressed vimentin, desmin, myoD1, and myogenin." (PMID 35001360, 2022). "Moreover, SRF::NCOA2 fusion-positive pediatric RMS (rhabdomyosarcoma) showing diffuse staining for desmin and multifocal nuclear positivity for myogenin are reported." (PMID 36421692, 2022). "Alveolar rhabdomyosarcomas are positive for Desmin, Myogenin, and Myo-D1." (PMID 34722090, 2021). "Similarly, alveolar rhabdomyosarcoma will show positivity for desmin, PEComas for smooth muscle actin and rhabdoid meningiomas will show eosinophilic inclusions strongly positive for EMA." (PMID 28744773, 2019). "The noncartilaginous spindled tumor cells were negative for MyoD1, myogenin, and desmin by immunohistochemical staining (data not shown), thus excluding the possibility that the noncartilaginous component was a variant of rhabdomyosarcoma." (PMID 27248819, 2016). "Also the bland cellularity of the myxoma and the negativity for desmin and Myogenin speak against a botryoid-type embryonal (myxoid) rhabdomyosarcoma, of the head and neck in children." (PMID 27064694, 2016). "The most useful immunohistochemical marker includes antibodies against muscle-specific actin and desmin, which show the greatest specifity, vimentin shows a positive reaction in most rhabdomyosarcoma but is less specific for this tumor because it can be positive in other malignancy." (PMID 24716058, 2014). "Coexpression of desmin and nuclear myoD1 was only detected in rhabdomyosarcoma." (PMID 24349741, 2013). "In addition, the IHC expression of muscle-specific markers such as desmin, myogenin, or myo-D1 is characteristic of rhabdomyosarcoma." (PMID 23762725, 2013). "Rhabdomyosarcoma usually express myogenic markers such as MyoD1 and desmin." (PMID 24349741, 2013). "Area of rhabdomyosarcoma express desmin and skeletal muscle markers, myogenin and myoD1." (PMID 21663687, 2011). "We further investigated the possibility of an alternative diagnosis including either a rhabdomyosarcoma or a melanoma, both of which have recurrent NRAS mutations, but the tissue was negative for all markers specific to these tumor types (SOX10, S100, myf4, and desmin)." (PMID 32191822, 2021).